CTSB (cathepsin B)
Diseases named in the same sentence as CTSB in open-access papers (continued):
Sharing a sentence is not in itself a finding about the gene and the disease.
liver fibrosis (19 papers, 2014 to 2025). "The overexpression of cathepsin B has also been described before causing liver fibrosis in patients with Niemann–Pick disease." (PMID 37628828, 2023). "VBY-376, a small-molecule CTSB inhibitor for hepatic fibrosis/NASH, demonstrates robust preclinical efficacy, favorable preliminary human safety, and progress into Phase II trials." (PMID 40943452, 2025). "Among the regulated downstream genes, the expression of genes encoding profibrotic cathepsin B and D was suppressed by PREP in macrophages, explaining the protective role of PREP against liver fibrosis." (PMID 37394591, 2023). "FSTL1 induces liver fibrosis through hepatic stellate cell activation; CTSB plays key roles in extracellular matrix (ECM) degradation and tissue remodeling, which drive hepatic stellate cell proliferation and promote fibrogenic potential." (PMID 32050622, 2020). "In contrast, cathepsin B demonstrated profibrotic potential in rodent hepatic fibrosis models by inducing hepatocyte apoptosis and promoting hepatic stellate cell proliferation." (PMID 31815017, 2019). "Next, we evaluated CTSB/S inhibition in animals with liver fibrosis, where an important inflammatory response to LPS was expected." (PMID 27831566, 2016). "Brenner reported that telomerase, b-cell lymphoma-extra large (Bcl-xL) and adiponectin genes are sensitive to fibrosis while Fas and cathepsin B genes are resistant to hepatocyte apoptosis and, thus, are resistant to hepatic fibrosis." (PMID 25280007, 2014). "The AUROC of cathepsin B was also calculated for each grade of the liver fibrosis." (PMID 36144371, 2022). "This is a lysosomal disease similar to NPCD, suggesting CTSB as a therapeutic target that may be relevant in the treatment of liver fibrosis in related LSDs." (PMID 34440927, 2021). "Interestingly, CTSB is increased and promotes liver fibrosis in a Niemann Pick type A (NPA) disease animal model." (PMID 34440927, 2021). "Additionally, cathepsin B was found to be involved in hepatic injury and in progression of liver fibrosis." (PMID 31060228, 2019). "Cathepsin B (CTSB) and cathepsin D (CTSD) are the two most abundant cathepsins in lysosomes and have been reported to play profibrogenic roles in liver fibrosis; therefore, we hypothesized that they might be the key to the mechanism underlying Prep knockout-induced exacerbated liver fibrosis." (PMID 37394591, 2023). "Therefore, macrophages could be regarded as the main source of these two profibrogenic proteins during liver fibrosis, which in turn indicates that the expression levels of CTSB and CTSD in homogenized liver tissue samples may roughly reflect their levels in hepatic macrophages in vivo." (PMID 37394591, 2023). "We aimed to determine the biomarker performance of the proteolytic enzymes cathepsin B (Cat B) and plasma kallikrein (PKa) and transforming growth factor (TGF)-β to detect hepatic fibrosis (HF) in chronic hepatitis C (CHC) patients." (PMID 36144371, 2022). "Taken together, these results show that cathepsin B was significantly superior to APRI (AUROC = 0.71 ± 0.05) and FIB4 (AUROC = 0.67 ± 0.06) in assessing significant liver fibrosis (control versus F2–4) in CHC patients." (PMID 36144371, 2022). "Importantly, we found that a subset of those proteins, CTSB, LIPA, DPP7, and GLMP had been previously connected with liver fibrosis, liver damage, and steatosis." (PMID 34440927, 2021). "In cattle, liver fibrosis has been proposed as a downstream effect of upregulated TNF and IL1B, which would activate the genes that were also upregulated in the bovine study, i.e., IL6, PLAU, SERPINE1, TNFRSF1A, SOCS1, and CTSB." (PMID 34616397, 2021). "Importantly, we found that lysosomal DEPs, including CTSB/D/Z, LIPA, DPP7 and GLMP, and mitocondrial DEPs, AKR1B10, and VAT1 had been connected with liver fibrosis, damage, and steatosis in previous studies, validiting our dataset." (PMID 34440927, 2021).
liver fibrosis (continued). "In particular, we have recently revealed the participation of cysteine cathepsins [Cathepsin B (CTSB) and Cathepsin S (CTSS)] in controlling hepatic NF-κB-dependent inflammation via sirtuin-1 regulation, and the role of CTSB in promoting hepatic stellate cell (HSC) activation and liver fibrosis." (PMID 29541077, 2018). "However, in Ncu-g1gt/gt liver the protein levels of cathepsin B and D are not elevated, indicating that the increased level of cell death and liver fibrosis observed in Ncu-g1gt/gt mice is not a result of an increased expression of these proteases." (PMID 24487409, 2014). "Interestingly, lysosomal proteins such as cathepsin B (CTSB), lysosomal acid lipase (LIPA), dipeptidyl peptidase 2 (DPP), and glycosylated lysosomal membrane protein (GLMP), which are known to be involved in liver fibrosis, liver damage, and steatosis, were found to be differentially expressed." (PMID 34440927, 2021). "Similarly, in a study of a mouse model of liver fibrosis, LPS/ATP treatment increases the contents of cathepsin B and ROS and activates NLRP3 inflammasome, while LPS/ATP and cathepsin B inhibitors fails to increase levels of NLRP3 and IL-1β." (PMID 37370025, 2023).
Arthritis (18 papers, 2005 to 2025). Inflammation of a joint. "With cellular damage, released CTSB has been proposed to contribute to multiple pathological conditions including inflammatory disease, arthritis, and nephropathy and has been shown to be associated with age related reduction in kidney function in women." (PMID 39968160, 2025). "Cathepsin B has been one of the most studied human cysteine cathepsins, especially after it was found to be linked with cancer and arthritis." (PMID 41465336, 2025). "Like MMPs -2 and -9, cathepsin B is associated with increased extracellular proteolysis in cancer and arthritis and has been considered a potential target for their treatment for decades." (PMID 33383850, 2020). "In addition, CTSB action is associated with joint inflammation, and elevated levels of cysteine cathepsins are present in synovial fluid and SF from RA patients as well as in the synovial membrane from RA and OA patients compared to controls." (PMID 34208590, 2021). "Cathepsin B is well known and has also been investigated for its involvement in pathological conditions, including its multiple roles in cancer, arthritis and Alzheimer’s disease." (PMID 33383850, 2020). "Similarly, our laboratory used a serum-induced arthritis mouse model to identify cathepsin B as one of the major proteases in the pro-IL-1β processing in the ROS-deficient Ncf1-/- mice." (PMID 29228045, 2017). "Moreover, increased CTSB activity and expression are shown in AC and cartilage from OA patients, and its levels in serum and synovial fluid correlate with severity and joint inflammation." (PMID 34208590, 2021). "Interestingly, other proinflammatory cytokines participating in arthritis, including IL-6, have been reported to activate cathepsin B and therefore could also trigger the cleavage of Sirt1." (PMID 23844973, 2013). "Furthermore, given the involvement of cathepsin B in neurobiological functions and neurodegenerative disease, tumor progression and arthritis, a better understanding of its function at the molecular level and of the mechanisms of cathepsin inhibition is desirable." (PMID 20920298, 2010). "Bone destruction (MMP3 serum levels, cathepsin B activity, and RANKL mRNA) peaked at day 3 after arthritis induction, followed by a peak in cartilage destruction and bone erosion on day 5 after arthritis induction." (PMID 26801240, 2016). "The role of cathepsin B, for instance in activation of pro-MMP-3 and its regulation in arthritis, was recently reviewed by Yan and Sloane." (PMID 15642138, 2005). "As a cytokine that mediates joint inflammation in arthritis, tumor necrosis factor α (TNF-α) was also found able to decrease SIRT1 activity and induce its cathepsin B-mediated cleavage and result in cartilage-specific gene expression inhibition in TNF-α-treated cells." (PMID 27863529, 2016). "Cathepsin B and H were non-significantly elevated on day 3 after the induction of experimental arthritis." (PMID 15642138, 2005).
asthma (18 papers, 2012 to 2025). "Additionally, cathepsin B protein encoded by CTSB gene at chr8p23.1 was previously reported to be higher among patients with asthma or COPD19,20." (PMID 38704398, 2024). "In COPD, the upregulation of CTSB may be related to long-term chronic inflammation and airway remodeling, whereas the downregulation of CTSB in asthma may be related to specific allergic response mechanisms and protective regulation." (PMID 40160461, 2025). "CTSB shows different modulation patterns in COPD and asthma, reflecting the different pathophysiological processes of the two diseases." (PMID 40160461, 2025). "PTGS2, IL10, CTSB, JAK2, and MTOR were significantly downregulated in alveolar lavage fluid with increasing asthma severity, while MMP9, GSK3B, BCL2, EGFR, and CCND1 were upregulated." (PMID 40160461, 2025). "CTSB, on the other hand, may have a similar role to ESR1, which is downregulated in alveolar lavage fluid in severe asthma as well as upregulated in bronchial epithelial cells in COPD." (PMID 40160461, 2025).
Chagas disease (17 papers, 2010 to 2026). A parasitic infection caused by Trypanosoma cruzi. "While no cathepsin B inhibitor has yet been approved for drug use, one has completed Phase 1 trials for fatty liver disease and another is in late preclinical stage for treating Chagas disease." (PMID 26388830, 2015).
leukemia (17 papers, 2011 to 2025). A malignant (clonal) hematologic disorder, involving hematopoietic stem cells and characterized by the presence of primitive or atypical myeloid or lymphoid cells in the bone marrow and the blood. "Conversely, in the whole lysate, CTSB was expressed in a mature form in all leukemia cells, while CTSD was expressed mainly as mature, with few amounts present in an immature form in each of the cell lines." (PMID 41227296, 2025). "In this study, we determine the effects of BEA on CTSB within granulocyte‐macrophage colony‐stimulating factor (GM‐CSF)‐cultured bone marrow‐derived dendritic cells (BMDCs) and human leukemia monocytic cell line THP‐1 induced immature dendritic cells (iDCs)." (PMID 40411408, 2025). "In hematological tumors, the relationship between CTSB and disease prognosis has already been reported for some leukemia cell lines." (PMID 37446393, 2023). "ASNase is mostly inactivated by proteases such as cathepsin B and asparagine endopeptidase, expressed by leukemia cells and macrophages." (PMID 33922106, 2021). "AEP and CTSB are expressed by Philadelphia positive (Ph+) and iAMP21 leukaemia cells, two very aggressive and poorly responsive forms of leukemia, while microenvironment cells such as macrophages can express CTSB and contribute to ASNase degradation." (PMID 29101342, 2017). "The correlation between Bid and cathepsin B in PTER-treated leukemia cells should be further confirmed in future work." (PMID 25144448, 2014). "We previously discussed that CA-074-OMe, the methylated variant of a highly specific inhibitor of cathepsin B abrogated the necrotic cell in caspase-inhibited leukemia cells, independently from its inhibitory effect on cathepsin B." (PMID 22860037, 2012). "Moreover, they are sensitive to proteases (cathepsin B and asparagine endopeptidase) that are over-expressed by resistant leukaemia lymphoblasts, thereby impairing drug activity and pharmacokinetics." (PMID 29101342, 2017). "In addition, degradation of Mcl-1 by cathepsin B plays a critical role on FTY720-induced leukemia apoptosis." (PMID 27528031, 2016). "For examples, cathepsin B degrades Mcl-1 proteins, resulting in apoptosis of FTY720-treated leukemia cells, and YM155 also induced down-regulation of Mcl-1 expression via lysosome-dependent manner in human oral cancer cells." (PMID 27582546, 2016). "Indeed, our current studies demonstrate that GSK-3β mediates ER stress-induced lysosomal apoptosis in leukemia involving caspase-2-induced LMP and cathepsin B relocation, which result in caspase-8 and -3 activation." (PMID 26727221, 2016). "We found that deletion of CTSB in REH ALL cells did not confer ASNase treatment sensitivity, thus suggesting that intrinsic expression of CTSB is not a mechanism that drives the resistant nature of these ALL cells to enzymes used as the first-line treatment against leukemia." (PMID 37446393, 2023). "Moreover, inhibition of cathepsin B activity induced apoptosis in AML cells, suggesting the contribution of this protease in the pathogenesis of this malignancy, but participation of cathepsins in other leukemias, such as ALL, deserve further investigation." (PMID 36500726, 2022).
ovarian tumor (16 papers, 2010 to 2024). "Immunohistochemical staining of tissue sections supported the notion that there is an increased amount of cathepsin B in ovarian tumor tissue compared to healthy ovarian tissue." (PMID 31484396, 2019).
rheumatoid arthritis (16 papers, 2015 to 2025). A chronic, systemic autoimmune disorder characterized by inflammation in the synovial membranes and articular surfaces. "Cathepsin B is often found in the synovial fluid of patients with rheumatoid arthritis and has been linked to articular cartilage degradation." (PMID 40135201, 2025). "Particular involvement of cathepsin B is reported in osteoarthritis and rheumatoid arthritis where it causes cartilage destruction." (PMID 35002435, 2022). "In rheumatoid arthritis and osteoarthritis, CTSB was found to contribute to joint damage by degrading type II collagen and proteoglycans in articular cartilage." (PMID 40422803, 2025). "In rheumatoid arthritis, research demonstrated that serum CTSB levels increase with disease activity, as it mediates synovial inflammation and cartilage degradation through protease activation." (PMID 41309848, 2025). "Increased levels of CTSB have been detected in synovial fluids of patients with rheumatoid arthritis and osteoarthritis, implying their participation in inflammation and cartilage destruction." (PMID 35740472, 2022). "Elevated levels of CTSB in fibroblasts are observed in inflammatory diseases, including rheumatoid arthritis." (PMID 35740472, 2022). "Cathepsin B overexpression results in the onset of osteoporosis, rheumatoid arthritis, and certain forms of cancers due to the excessive degradation of the proteins aggrecan, tenascin C, fibronectin, and collagen type 1." (PMID 34827106, 2021). "Interestingly, traits like platelet-to-lymphocyte ratio, sphingomyelin, cathepsin B, and LILRB2 protein levels have been positively associated with rheumatoid arthritis." (PMID 39175752, 2024). "Finally, synovial fluid (SF) and serum from donors with no signs of diseases, early OA, late OA and rheumatoid arthritis (RA) patients were analyzed with GB123 to detect distinct activity levels of cathepsin B and S." (PMID 25889265, 2015).
colitis (15 papers, 2018 to 2025). Inflammation of the colon. "In our data, we only observed one significantly altered cleavage event occurring after aspartic acid (cathepsin B), which was enriched only in Lgmn−/− colitis tissue compared to Lgmn−/− naïve." (PMID 39392222, 2025). "Of note, in vivo studies determined that the expression and activity of cytoplasma cathepsin B were reduced in the colonic epithelial cells from mannose-treated colitis mice compared to those from control mice." (PMID 35974017, 2022). "The level of activated cathepsin B was increased significantly in the colon tissues from the DSS-induced colitis model mice, as indicated by immunoblotting and immunohistochemical staining." (PMID 35974017, 2022). "Interestingly, PC3-EV exposure induces an increase in cathepsin B cleaved/active form mediated by ERK1/2 activation as recently shown in DSS-induced colitis where inflammasome activation, superimposed by deoxycolic acid, is triggered by ERK1/2 and cathepsin B." (PMID 31480312, 2019). "Inhibition of both CTSB and CTSD has been shown to ameliorate DSS colitis and overexpression of MMP-9 to aggravate DSS and infectious colitis." (PMID 39200138, 2024). "DCA enema significantly aggravated DSS-induced colitis in mice and S1PR2 inhibitor as well as inflammasome inhibition by cathepsin B antagonist substantially reducing the mature IL-1β production and alleviated colonic inflammation superimposed by DCA." (PMID 29854830, 2018). "DCA enema strongly aggravates DSS-induced colitis in mice and S1PR2 antagonist as well as inhibition of cathepsin B substantially alleviate colonic inflammation imposed by DCA." (PMID 29854830, 2018). "Zhenhu Zhang’s study demonstrated significantly higher expression levels of CTSL in ESCC tissues than adjacent non-cancerous tissues; Shengnan Zhao’s research revealed increased cathepsin B levels in colonic tissue and exacerbated dextran sodium sulfate (DSS)-induced colitis." (PMID 39359476, 2024). "DCA induces NLRP3 inflammasome activation mainly via promoting cathepsin B release and colorectal instillation of DCA could significantly exacerbate DSS-induced colitis through activating NLRP3 inflammasome." (PMID 29854830, 2018). "In contrast, glucose treatment did not influence the cathepsin B activation in DSS-induced colitis model mice and IL-10−/− colitis mice." (PMID 35974017, 2022).
neuroblastoma (15 papers, 2007 to 2025). Neuroblastoma (NB) is the most common solid, extracranial childhood tumor. "Inhibition of cathepsin B or L has been reported to cause NPC‐like cholesterol sequestration in human neuroblastoma." (PMID 33931944, 2022). "Firstly, we show that inhibition of CtsB/L in CHOwt and in human neuroblastoma SH-SY5Y cells causes substantial lysosomal dysfunction." (PMID 27902765, 2016). "Previously, we demonstrated that FD disrupts the autophagic-lysosomal pathway in neuroblastoma cells and fish brain by down-regulating cathepsin B expression, which led to Alzheimer's-like pathology." (PMID 38956599, 2024). "To address a possible common role of highly expressed and functional important CTS proteases, we generated CTSB-, CTSD-, CTSL-, and CTSBDL-triple deficient (KO) human neuroblastoma-derived SH-SY5Y cells and CTSB-, CTSD-, CTSL-, CTSZ and CTSBDLZ-quadruple deficient (KO) HeLa cells." (PMID 38775843, 2024). "For instance, bis-(2-ethyl heptyl) phthalate inhibited cathepsin B with an IC50 value of 121.22 μg/ml, causing neuroblastoma cell death in comparison with compound 2 presented in this study that exhibited a slight decrease in IC50 values against HepG-2 and A-431 cell lines." (PMID 38796482, 2024). "Furthermore, pull-down of the AMPylated proteins from neuroblastoma cells under FICD E234G OX conditions revealed a general increase in AMPylation including proteins such as CTSB, TPP1, CAPZB, and NSFL1C, which were found AMPylated in COs." (PMID 31980631, 2020). "In order to test the possibility that the mechanism of protection by CysC involves inhibition of cathepsin B, cathepsin B expression and specific activity were measured in neuroblastoma cells under serum-deprivation conditions in the presence or absence of CysC." (PMID 20352108, 2010). "Significant reduction in the lysosomal degradation capacity, substantially enlarged lysosomes, and increased lysosome number were observed in the CTSB and CTSL double knockout human neuroblastoma cells." (PMID 35806091, 2022). "For instance, CST3 increases neuron viability by inhibiting autophagy and cathepsin B (Cat B) in Cu/Zn-superoxide dismutase (SOD1)-mutant, or cytotoxicity-exposed neuroblastoma cell lines and primary cultured motor neuronal cells." (PMID 32733872, 2020). "Here, we show that CtsB/L inhibition in CHO and in human neuroblastoma SH-SY5Y cells as well as CtsB and CtsL genetic depletion also affects NPC1 and/or NPC2 and causes their sequestration and accumulation of intracellular free cholesterol." (PMID 27902765, 2016).